RAD51B (RAD51 paralog B)
Diseases named in the same sentence as RAD51B in open-access papers (continued):
Sharing a sentence is not in itself a finding about the gene and the disease.
leiomyoma (4 papers, 2020 to 2024). A well-circumscribed benign smooth muscle neoplasm characterized by the presence of spindle cells with cigar-shaped nuclei, interlacing fascicles, and a whorled pattern. "Early cytogenetic studies on leiomyomas and other benign mesenchymal tumors identified RAD51B as the most common translocation partner for HMGA2, often in the form of a balanced translocation." (PMID 35822448, 2023). "RAD51B may be a fusion partner of HMGA2 and HMGA1 but can occur in fusion with other genes including NUDT3 and seems to be a potential driver event in these tumors mutually exclusive with other driver aberrations defining molecular leiomyoma subtypes." (PMID 37466765, 2024).
melanoma (4 papers, 2016 to 2025). A malignant, usually aggressive tumor composed of atypical, neoplastic melanocytes.
gastric cancer (3 papers, 2017 to 2022). A primary or metastatic malignant neoplasm involving the stomach. "Intriguingly, in contrast to our findings on RAD51B, others showed that hyperexpression of RAD51B in a subset of GC (Gastric Cancer) was significantly associated with poor prognosis and resistance to chemotherapy." (PMID 29207658, 2017). "In gastric cancer, RAD51B specifically has been identified as a potential biomarker for poor prognosis." (PMID 30713603, 2019). "Additionally, functional studies indicated that over-expression of RAD51B promoted the proliferation of gastric cancer cell, while RAD51B knockdown led to G1 arrest, suggesting that RAD51B may act as an oncogene during gastric cancer progression." (PMID 35812748, 2022).
glioma (3 papers, 2016 to 2023). A benign or malignant brain and spinal cord tumor that arises from glial cells (astrocytes, oligodendrocytes, ependymal cells). "In conclusion, an enhancer variant of RAD51B rs6573816 was identified as a novel susceptibility and progression locus for glioma." (PMID 37858068, 2023). "In the present study, we also found that the rs6573816 C allele, which was identified as a protective allele for glioma development and drove lower expression of RAD51B, increased the risk of glioma progression in a sex-dependent manner." (PMID 37858068, 2023). "In the present study, we found that an enhancer variant of RAD51B rs6573816 was associated with glioma susceptibility, which implies a significant role of RAD51B in glioma development." (PMID 37858068, 2023). "A case–control study consisting of 1056 individuals was conducted to evaluate the associations of enhancer variants of RAD51B with glioma susceptibility and progression." (PMID 37858068, 2023). "Of note, the rs6573816 C allele driving lower expression of RAD51B was found to decrease the risk of glioma significantly." (PMID 37858068, 2023). "In the present study, an enhancer variant of RAD51B rs6573816 was found to be significantly associated with glioma susceptibility and progression in a sex-dependent manner." (PMID 37858068, 2023). "Therefore, it is worthwhile to evaluate the role of enhancer variants of RAD51B in glioma development and progression." (PMID 37858068, 2023). "In this study, we conducted a case–control study consisting of 402 glioma patients and 654 controls to investigate whether enhancer variants of RAD51B confer susceptibility and progression to glioma." (PMID 37858068, 2023). "However, the significance of enhancer variants of RAD51B in glioma susceptibility and progression remains unclear." (PMID 37858068, 2023). "Logically, our findings indicate that overexpression of RAD51B might be a risk factor for glioma." (PMID 37858068, 2023). "While, overexpression of RAD51B might function as a susceptibility factor for glioma." (PMID 37858068, 2023). "We further explored the relationship between the expression of POU2F1 and RAD51B in lymphoblastic cells and glioma tissues." (PMID 37858068, 2023). "Consistently, positive correlation between the expression of POU2F1 and RAD51B was found in lymphoblastic cells and glioma tissues." (PMID 37858068, 2023).
Gynecomastia (3 papers, 2020 to 2022). Abnormal development of large mammary glands in males resulting in breast enlargement. "The gene promoters that showed statistically significant differences between tumor and gynecomastia samples (RAD51B and XRCC3) were evaluated as potential biomarkers for male BC." (PMID 32295201, 2020). "The RAD51B and XRCC3 signatures can accurately discriminate MaBC from gynecomastia, with normal breast tissues showing methylation of these gene promoters at lower levels than in MaBC, suggesting the existence of a tumorigenesis pathway." (PMID 35373955, 2022). "Remarkably, the methylation panel in tissue samples combining RAD51B and XRCC3 accurately discriminated MBC from gynecomastia." (PMID 34298749, 2021). "Surprisingly, however, higher RAD51B and XRCC3 promoter methylation levels were disclosed in gynecomastia comparing to male BC." (PMID 32295201, 2020). "Remarkably, the methylation panel combining RAD51B and XRCC3 accurately discriminated male BC from gynecomastia, in tissue samples." (PMID 32295201, 2020). "Only RAD51B and XRCC3 disclosed statistically significant differences between tumor and gynecomastia tissues, with higher methylation levels observed in gynecomastia tissue samples." (PMID 32295201, 2020). "Assembled in a panel, RAD51B and XRCC3 promoter methylation discriminated male BC from gynecomastia with 91.5% sensitivity, 89.5% specificity, and 91.2% accuracy." (PMID 32295201, 2020). "In this study we demonstrated that promoter methylation levels of RAD51B and XRCC3 differ between male BC and gynecomastia tissues, suggesting its usefulness, in a panel, as male BC biomarkers." (PMID 32295201, 2020). "ATM, BRCA1, PALB2, RAD51B, and XRCC3 promoter methylation levels were evaluated in paired tumor, normal tissue, and adjacent lymph nodes, and in gynecomastia tissue samples." (PMID 32295201, 2020). "Thus, although RAD51B and XRCC3 promoter methylation levels might be higher in gynecomastia, histone-related factors might preclude effective gene silencing, contrarily to BC." (PMID 32295201, 2020). "ATM, BRCA1, PALB2, RAD51B, and XRCC3 have epigenetic signatures in MaBC that are absent in corresponding normal tissue and gynecomastia samples obtained from patients without cancer or with a family history of BC." (PMID 35373955, 2022). "The epigenetic signatures of ATM, BRCA1, PALB2, RAD51B, and XRCC3 have also been explored in MBC (32.4% with germline BRCA2 PV) in matched normal and gynecomastia tissue samples (obtained from patients without cancer or a family history of BC)." (PMID 34298749, 2021). "Among the five gene promoters tested, only two - RAD51B and XRCC3—disclosed statistically significant differences between tumor and gynecomastia tissue samples, whereas ATM, BRCA1, and PALB2 did not." (PMID 32295201, 2020).
non-small cell lung carcinoma (3 papers, 2017 to 2020). A group of at least three distinct histological types of lung cancer, including non-small cell squamous cell carcinoma, adenocarcinoma, and large cell carcinoma. "We examined the methylation profile of RAD51B (RAD51Bme) as a candidate predictive biomarker for anti-PD-1 therapy efficacy in non-small cell lung cancer (NSCLC), correlating with patients’ outcome." (PMID 32252414, 2020). "In our study, we describe a significant result from data analysis, proposing for the first time the function of RAD51B in the prognosis of non-small-cell lung carcinoma patients." (PMID 29207658, 2017). "In our study, we propose that RAD51B, a repair gene in the homologous recombination process, which is noticed to be a key player in the maintenance of chromosome integrity and in sensing DNA damage, can act as an independent factor affecting the prognosis of non-small-cell lung cancer (NSCLC)." (PMID 29207658, 2017). "Herein, we took advantage of TCGA data, screening candidate DNA-repair genes (RAD51B, RAD51C, RAD51D, XRCC2, and XRCC3) with covariance and correlation matrices in mRNA level from complete 1124 complete cases of non-small cell lung cancer clinical data." (PMID 29207658, 2017).
pancreatic cancer (3 papers, 2020 to 2025). "In the Nira-Panc study, the effectiveness of a monotherapy with the PARP inhibitor niraparib had already been investigated in first-line progressive pancreatic cancer with a RAD51B mutation, among others (6-month PFS rate of 40%, median PFS of 4.4 months, median OS of 9.1 months)." (PMID 40963850, 2025).
rheumatoid arthritis (3 papers, 2017 to 2024). A chronic, systemic autoimmune disorder characterized by inflammation in the synovial membranes and articular surfaces. "RAD51B polymorphisms were associated with rheumatoid arthritis and erosion in patients with rheumatoid arthritis patients." (PMID 38473866, 2024). "Also, RAD51B rs911263 was associated with rheumatoid arthritis (RA); two SNPs (rs11158728 and rs927220) were associated with nasopharyngeal carcinoma development, and one (rs34094401) was associated with Parkinson's disease." (PMID 31191752, 2019).
asthma (2 papers, 2022 to 2023). "Moreover, a whole-genome sequencing association study of asthma severity in Europeans evidenced eight genome-wide significant loci previously reported as associated with asthma (IL1RL2, TSLP, HLA-DQA1, BACH2, C11orf30, RAD51B, and GSDMB) and lung function (THSD4)." (PMID 37761964, 2023).
breast tumor (2 papers, 2022 to 2025). "Here we found significantly lower methylation of CD160, ISYNA1 and RAD51B were correlated with hormone receptor status, increased breast tumor size, advanced tumor stage and more lymph node involvement." (PMID 35812748, 2022).
head and neck squamous cell carcinoma (2 papers, 2016). A squamous cell carcinoma that arises from any of the following anatomic sites: lip and oral cavity, nasal cavity, paranasal sinuses, pharynx, larynx, and salivary glands. "In addition to recurrent integrations in RAD51B, NR4A2, and TP63, additional genomic alterations were found in receptor tyrosine kinases, primarily FGFR2 and FGFR3, in HPV-positive head and neck squamous cell carcinoma." (PMID 27154171, 2016).
leiomyosarcoma (2 papers, 2023 to 2024). An uncommon, aggressive malignant smooth muscle neoplasm, usually occurring in post-menopausal women. "We also observed a trend towards higher median TERRA levels in POT1 altered angiosarcoma vs WT (12.5 vs 5.8, p > 0.05) and a trend towards higher levels in RAD51B altered uterus leiomyosarcoma vs WT (46.7 vs 30.1, p > 0.05)." (PMID 37709802, 2023). "Within uterus leiomyosarcomas, 84.2% of the identified RAD51B alterations were copy number deletions." (PMID 37709802, 2023). "Similarly, in ATRX altered uterus leiomyosarcoma, RAD51B alterations exerted an additive effect on telomeric elongation (2226 TRPM in double-altered vs 1449 in RAD51B altered only and 812 in ATRX altered only)." (PMID 37709802, 2023).
lung adenocarcinoma (2 papers, 2017 to 2018). A carcinoma that arises from the lung and is characterized by the presence of malignant glandular epithelial cells. "The distinct roles of RAD51B in lung squamous cell carcinoma and lung adenocarcinoma may be contributed to the presence of different signaling pathways or growths factors in these two histopathology types." (PMID 29207658, 2017).
ovarian tumors (2 papers, 2021 to 2022). "Prior genomic data derived from whole genome-sequenced ovarian tumors have suggested that RAD51B inactivation may be associated with an enrichment of foldback inversions, a structural variant characterized by inverted duplications." (PMID 34635660, 2021). "Beyond these mutations, germline or somatic aberrations in genes of the homologous recombination (HR) pathway such as RAD51B/C/D, PALB2, ATM, BRIP1 may confer an HR deficiency in up to 50% of ovarian tumors." (PMID 36531003, 2022).
PEComas (2 papers, 2024 to 2025). "A smaller subset of PEComas harbors rearrangements involving TFE3 or RAD51B." (PMID 40647483, 2025). "Additionally, the novel RAD51B gene fusion is observed exclusively in uterine PEComas." (PMID 39759135, 2024).
sarcoma (2 papers, 2022 to 2023). A usually aggressive malignant neoplasm of the soft tissue or bone. "Prevalence of RAD51B, GID4, and POT1 alterations varied widely across sarcoma subtypes and tended to mostly occur in diseases with high prevalence rates of alterations in the other telomere maintenance genes." (PMID 37709802, 2023). "Across all sarcoma samples within our screening cohort, samples with alterations in either GID4, RAD51B, POT1, or ATRX had significantly higher telomeric content than WT samples." (PMID 37709802, 2023). "Our results propose a role played by RAD51B and GID4 in telomere elongation in sarcomas and open research opportunities for agents aimed at targeting this critical pathway in tumorigenesis." (PMID 37709802, 2023).
soft tissue sarcoma (2 papers, 2020 to 2023). A malignant neoplasm arising from muscle tissue, adipose tissue, blood vessels, fibrous tissue, or other supportive tissues excluding the bones. "Overall, the alteration prevalence for these genes was low, where GID4 was altered in 3.6% (83/2332) of soft tissue sarcoma nos, POT1 in 6.3% (38/606) of angiosarcoma, and RAD51B in 3.6% (38/1055) of uterus leiomyosarcoma samples." (PMID 37709802, 2023).
triple-negative breast carcinoma (2 papers, 2015 to 2021). An invasive breast carcinoma which is negative for expression of estrogen receptor (ER), progesterone receptor (PR), and human epidermal growth factor receptor 2 (HER2). "This study and others, have also demonstrated that carriers of pathogenic RAD51C/D mutations tend to develop triple-negative breast cancers, in contrast to the predominantly (4 of 5 cases) hormone receptor-positive breast cancers identified among carriers of RAD51B mutations in our cohort." (PMID 34635660, 2021).
angioedema (1 paper, 2025). Swelling involving the deep dermis, subcutaneous, or submucosal tissues, representing localized edema. "We also found SNPs located close to the genes PRKCQ (protein kinase C theta), RAD51B (RAD51 Paralog B), and RIMS1 (regulating synaptic membrane exocytosis 1), which have previously been linked with drug-induced angioedema." (PMID 41189626, 2025).
astrocytomas (1 paper, 2023). "In IDHmut astrocytomas and all diffuse gliomas, RAD51B loss was associated with worse OS (p < 0.05, log-rank test)." (PMID 37932833, 2023). "In grade 3–4 IDHmut astrocytomas, loss of RAD51B was associated with increased proliferation, which was also partly reflected in the HRR and FA activity scores." (PMID 37932833, 2023). "In the TCGA data, recurrent hemizygous RAD51B losses were detected, including in a recurrent IDHmut astrocytoma case with prior radiation, and led to significantly decreased RAD51B expression." (PMID 37932833, 2023).
autoimmune disease (1 paper, 2022). A disorder resulting from loss of function or tissue destruction of an organ or multiple organs, arising from humoral or cellular immune responses of the individual to their own tissue constituents. "Genetic studies have identified ethnic differences in gene polymorphisms of CD160 in autoimmune diseases and RAD51B in BC." (PMID 35812748, 2022).
bladder cancer (1 paper, 2022). "Another report on 98 patients with bladder cancer showed that mutations in DNA repair genes (CHEK2, ERCC5, GEN1, MLH1, PALB2, RAD50, RAD51B and RECQL4) are associated with an unfavorable cancer prognosis and 22% of patients had a mutation." (PMID 35395863, 2022).
bladder tumors (1 paper, 2020). "Of note, the five mutated bladder tumors in the AGATCA core motif of RAD51B were also mutated for at least one of the 18 TGAACA core motif loci." (PMID 33049910, 2020).
chordoma (1 paper, 2021). Chordomas are rare malignant tumors arising from embryonic remnants of the notochord in axial skeleton. "The gene expression data also showed downregulation of RAD51B gene at E-SOBP of proton treatment, which is unable to activate recombinational repair, and therefore causes more chordoma cell death." (PMID 34885223, 2021). "In addition, we also identified downregulation of homologous recombination gene RAD51B in E-SOBP cells, which impacts cellular ability to repair lethal double strand breaks in chordoma cells." (PMID 34885223, 2021).
Ewing sarcoma (1 paper, 2024). A small round cell tumor that lacks morphologic, immunohistochemical, and electron microscopic evidence of neuroectodermal differentiation. "The NTRK gene and fusion partner was TPM3::NTRK1 (fibrosarcoma), LPPR1::NTRK2 (Ewing’s sarcoma), DAB2IP::NTRK2 (primitive neuroectodermal tumor), and RAD51B::NTRK3 (PTC)." (PMID 38967220, 2024). "Among pediatrics there was one case each of fibrosarcoma (TPM3::NTRK1), Ewing’s sarcoma (LPPR1::NTRK2), primitive neuroectodermal tumor (DAB2IP::NTRK2), and papillary thyroid carcinoma (RAD51B::NTRK3)." (PMID 38967220, 2024). "The other two NTRK gene fusions in pediatrics were an LPP1::NTRK2 fusion (Ewing’s sarcoma), and a RAD51B::NTRK3 (PTC); we did not identify ETV6::NTRK3, TPR::NTRK1 – NTRK gene fusions were more commonly reported among pediatrics with solid tumors." (PMID 38967220, 2024).
familial ovarian cancer (1 paper, 2016). An instance of ovarian cancer that is caused by an inherited modification of the individual's genome. "We sequenced the coding region and the exon-intron boundaries of the RAD51B gene in 168 breast (female and male) and 4 familial ovarian cancer patients from Southern Finland." (PMID 27149063, 2016).
leukemia (1 paper, 2023). A malignant (clonal) hematologic disorder, involving hematopoietic stem cells and characterized by the presence of primitive or atypical myeloid or lymphoid cells in the bone marrow and the blood. "Given the potential importance of RAD51B in processing damaged DNA in haploid leukemia, we asked if RAD51B and the HR pathway were involved in the in vivo response to DNA-damaging chemotherapy in near-haploid B-ALL." (PMID 37286545, 2023). "Nevertheless, we anticipate that future multi-omic profiling approaches would yield deeper insights into the role of RAD51B in near-haploid leukemia cells and help validate its potential as a therapeutic target." (PMID 37286545, 2023). "Combining cell cycle stage-specific differential expression with gene essentiality scores from a genome-wide CRISPR-Cas9-mediated knockout screen, we identified the homologous recombination pathway component RAD51B as an essential gene in near-haploid leukemia." (PMID 37286545, 2023). "Together, these results imply that near-haploid and diploid/near-diploid cells show differential requirements for RAD51B expression and sensitivity to G2/M checkpoint regulations, and that RAD51B may be a promising candidate for targeted therapy in this challenging subtype of leukemia." (PMID 37286545, 2023).
lipoblastoma (1 paper, 2023). A lipoma usually occurring in the extremities of young children (usually boys). "RAD51B has also been reported as a translocation partner for PLAG1 in lipoblastomas." (PMID 35822448, 2023).
Obesity (1 paper, 2018). Accumulation of substantial excess body fat. "Moreover, we observed candidate association of rs6271 in the DBH gene, rs62618693 in the QSER1 gene, and variants in PCDHA1, RAD51B, and PLEKHA5 with non-T2D-linked obesity." (PMID 30126146, 2018).